LAG3 (lymphocyte activating 3)
Diseases named in the same sentence as LAG3 in open-access papers (continued):
Sharing a sentence is not in itself a finding about the gene and the disease.
melanoma (continued). "It is highly expressed in the liver and melanoma cells, where it inhibits the immune responses of CD8+ T cells and NK cells through its interaction with LAG-3." (PMID 40356928, 2025). "Currently three different types of immune checkpoint inhibitors (ICIs) are approved for the treatment of advanced melanoma: CTLA-4 inhibitor (ipilimumab), PD-1 inhibitor (pembrolizumab and nivolumab) and LAG-3 inhibitor (relatlimab)." (PMID 40507314, 2025). "Examples include lymphocyte-activation gene 3 (LAG-3), with its effectiveness again pioneered in patients with advanced melanoma, leading to FDA approval of the drug relatlimab in 2022." (PMID 38476371, 2024). "Particularly, the combination therapy of relatlimab (anti-LAG-3 mAb; BMS-986016) with nivolumab (anti-PD-1 mAb) has demonstrated impressive clinical effectiveness in melanoma patients unresponsive to anti-PD-1/PD-L1 therapy." (PMID 38375475, 2024). "Their findings revealed that LAG-3 was expressed in CD8+ T cells and exhibited high expression in NK cells and Tregs among melanoma patients." (PMID 38390331, 2024). "Relatlimab, a LAG-3 inhibitor, has been employed in the treatment of advanced melanoma, with ongoing clinical trials evaluating various LAG-3 inhibitors, underscoring the potential of LAG-3 as a promising therapeutic target in melanoma treatment." (PMID 39743998, 2024). "In a randomized trial, the phase II/III study revealed that the anti-LAG-3 therapeutic relatlimab, when used alongside nivolumab (anti-PD-1), led to a 12-month progression-free survival (PFS) rate of 47.7% in melanoma patients." (PMID 39252941, 2024). "According to their research, LAG-3 was highly expressed on CD8+ T cells, NK cells, and Tregs in melanoma patients." (PMID 39660130, 2024). "CXCL13 was found to be preferentially enriched in dysfunctional CD8+ T cells within the melanoma ecosystem, and together with TIGIT, PDCD1 and LAG3, it has been used to define the dysfunctional state of T cells." (PMID 38519500, 2024). "The development of LAG-3 inhibitors has garnered widespread attention globally, particularly after the FDA approval of Relatlimab for melanoma treatment." (PMID 39743998, 2024). "Recent data suggest that LAG-3 represents an emerging target for ICB, as LAG-3 inhibition has yielded promising results in melanoma." (PMID 37046760, 2023). "Lastly, we observed in inverse relationship between baseline and on-treatment levels of circulating LAG3-expressing CD8 memory T cells and response to combination PD-1 and CTLA4 blockade in a clinical trial cohort of patients with melanoma." (PMID 37795090, 2023). "When LAG-3 blockade antibody (BMS-986016) and nivolumab (a PD-1 antibody) were used in combination in melanoma patients, the initial resistance when only blocking of the PD-1/PD-L1 axis was converted." (PMID 36960057, 2023). "As immune checkpoint receptors such as LAG-3, PD-1, and TIM-3 offer a promising new approach for the treatment of advanced melanoma, we focused on finding a new tool to modulate their expressions." (PMID 37895833, 2023). "Recently, the co-inhibition of LAG-3 by relatlimab and that of PD-1 by nivolumab revealed a greater antitumor activity than that of nivolumab alone in a randomized phase III study on melanoma." (PMID 37179337, 2023). "Recent studies indicate that melanoma cells expressing MHC class II molecules attract a specific infiltration of CD4+ T cells, potentially facilitated by the interaction between LAG3 and MHC class II molecules." (PMID 37569880, 2023). "Inhibitors of LAG-3 have already reached phase II and phase III clinical trials and relatlimab has been approved in combination with nivolumab for advanced melanoma." (PMID 37296957, 2023). "Different combinations of INCAGN02390 with PD-1 and LAG-3 blocking agents are being evaluated in a phase-I/II study (NCT04370704) for patients with advanced cancers, including melanoma." (PMID 37345056, 2023).
melanoma (continued). "Melanoma has been at the forefront of immunotherapy with at least three checkpoint targets to date, namely PD-1, CTLA-4, and LAG-3, being first FDA approved in metastatic disease." (PMID 37484526, 2023). "Our comprehensive multiomics data set demonstrates that LAG3 is not only expressed in CD8+ T cells but that it is also highly expressed in NK cells and Tregs of patients with melanoma." (PMID 36719749, 2023). "LAG-3 is expressed on a subset of human pDCs, and LAG-3+ pDCs are enriched in the tumor sites of melanoma patients." (PMID 37670328, 2023). "More recently, relatlimab, a lymphocyte-activation gene 3 (LAG-3)–blocking antibody that functions to reduce LAG-3 mediated T cell inhibition, has been developed and used as an additional immunotherapy for melanoma." (PMID 37444454, 2023). "Clinical management of melanoma LMD consists primarily of radiation therapy, BRAF/MEK inhibitors as targeted therapy, and immunotherapy with anti-PD-1, anti-CTLA-4, and anti-LAG-3 immune checkpoint inhibitors." (PMID 36980770, 2023). "Further, combined LAG-3 and PD-1 ICI therapy has shown increased survival in Stage IV melanoma patients compared to single PD-1 blockade application." (PMID 37344517, 2023). "Chronic exposure of B16 mouse melanoma cells to IFN-γ stimulates the expression of the checkpoint receptors PD-1, CTLA-4, LAG-3, and of TIM-3 ligands, as well as the resistance to combined ICB therapies in tumor grafts." (PMID 38304252, 2023). "Consistent with our model prediction, LAG3 and HAVCR2 have been previously shown to have high correlation with a dysfunctional “exhausted” phenotype in CD8+ CTLs in melanoma." (PMID 37182110, 2023). "As melanoma cells often express MHC class II, binding of LAG-3 to tumor-infiltrating T cells can result in potent immune suppression and, ultimately, immune evasion by melanoma." (PMID 36831449, 2023). "Melanoma cells express MHC II molecules and attract tumor-specific CD4+ T-cells probably via LAG-3 interaction which negatively affects the response of CD8+ T-cells." (PMID 37509517, 2023). "Melanoma cells expressing MHC class II attract the infiltration of tumor-specific CD4+ T cells, possibly through interactions with LAG-3, which in turn negatively affects the CD8+ T cell response." (PMID 36077354, 2022). "In some tumors, such as ovarian, melanoma, non-small-cell lung cancer (NSCLC), and gastrointestinal cancers, PD-1 was usually co-expressed with LAG3." (PMID 36013315, 2022). "Phase I trials of the monoclonal antibody INCAGN02390 as monotherapy or in combination with inhibitors of PD-1, LAG-3, IDO1, or FGFR for solid tumors and melanoma therapy are ongoing." (PMID 36140182, 2022). "In some melanoma patients, CTLA-4 inhibition has been found to elicit an increase in the frequency of LAG3+ TILs." (PMID 35434132, 2022). "Considering that co-inhibitory molecules have been explored to promote anticancer T-cell responses and constitute therapeutic targets in the treatment of melanoma, we decided to assess the transcriptional levels of TIM-3 and LAG-3 in PBMCS exposed to iSec." (PMID 35419291, 2022). "In melanoma and NSCLC tumors, the blockade of LAG3 exerts antitumor effects in patients with positive LAG3 expression, and several studies are ongoing for other solid tumors." (PMID 36013315, 2022). "Furthermore, the expression of ICIs between high- and low-risk melanoma patients were analyzed, indicating that the expression of immune-regulatory proteins (IRPs) such as PD-1 (PDCD1), PD-L1 (CD274), CTLA-4, HAVCR2 (TIM3), CD8, and LAG3 was significantly lower in the high-risk group (p < 0.05)." (PMID 35326741, 2022). "Recent findings published on anti LAG-3 agent relatlimab have opened a completely new perspective on metastatic melanoma treatment with really encouraging data in terms of PFS that, if confirmed in OS, may lead to a new standard of treatment both for WT and BRAF mutated melanoma." (PMID 35160279, 2022).
melanoma (continued). "In melanoma mouse models, 9-ING-41 downregulates the expression of inhibitory immune checkpoints including PD-1 and LAG-3, resulting in synergistic anti-tumor activity when administered in combination with immune checkpoint inhibitors." (PMID 34356465, 2021). "LAG-3+ pDCs possess high potentials in producing IL-6, which suppresses the immune system via STAT3 signaling and leads to melanoma metastasis." (PMID 32902664, 2021). "A number of identified molecules, including TNFRSF13B, LAG3, NRP1, ENTPD1, NT5E, CCL21, and CCR7, can serve as future therapeutic targets in the treatment of melanoma." (PMID 34159752, 2021). "Further to this, increased antitumor immunity to B6 melanoma cells was observed using a combination of both GSK-3 inhibition and antibody blockade of LAG-3." (PMID 33946954, 2021). "Among them, MIR205HG expression is associated with the poor outcome of patient and its expression is positively correlated with the expressions of immune checkpoints like PD-1, CTLA4, LAG3, and TIM3 in adenocarcinoma and melanoma." (PMID 35096622, 2021). "Thus, MHC class II ligation of LAG-3 could induce melanoma-infiltrating T cell exhaustion." (PMID 34572799, 2021). "Among the ongoing clinical trials of mAbs targeting LAG3, IMP321 and relatlimab trials have progressed rapidly in recent years, showing a favorable anti-tumor effect in melanoma." (PMID 35111155, 2021). "Enhanced expression of LAG-3 has been detected on CD4+ and CD8+ T cells infiltrating into metastatic lymph nodes of patients suffering from melanoma." (PMID 32902664, 2021). "Recent results in melanoma (phase III RELATIVITY-047 trial) were published at ASCO, revealing that a combination of LAG-3 antibodies with anti-PD-1 increased the progression free survival to 10.1 months compared to nivolumab alone (4.6 months)." (PMID 34572799, 2021). "A number of identified molecules including TNFRSF13B, LAG3, NRP1, ENTPD1, NT5E, CCL21, and CCR7 can serve as future therapeutic targets in melanoma treatment." (PMID 34159752, 2021). "While anti-LAG-3 has shown little effect as monotherapy, dual anti-LAG-3/anti-PD-1 treatment exerted potent anti-tumor effects in mice with melanoma and colon carcinoma." (PMID 34439292, 2021). "The synergistic inhibitory effect of LAG3 and PD-1 on T cells has been confirmed in a variety of tumors, including NSCLC, melanoma, renal cell carcinoma (RCC), head and neck cancer, and breast cancer." (PMID 34526102, 2021). "The effectiveness of the combination of INCMGA00012 (anti-PD-1 antibody), INCAGN02385 (anti-LAG-3 antibody), and INCAGN02390 (anti-TIM-3 antibody) is under evaluation in a phase I/II clinical study in melanoma patients (NCT04370704)." (PMID 33167514, 2020). "Another phase I/II clinical trial is assessing the effective combination of anti-LAG-3, anti-PD-1, and anti-TIM-3 in melanoma (NCT04370704)." (PMID 33167514, 2020). "Lag-3+ Tregs produces high amounts of IL-10 and transforming growth factor beta (TGF-β) and expand in tumor tissue of patients with melanoma and colorectal cancer." (PMID 33101304, 2020). "In the present study, we found two notable results; first, PD-1 and LAG-3 correlated with the CD163 expression, suggested as a poor prognostic factor in melanoma." (PMID 32756500, 2020). "LAG3 interaction with its ligands galectin 3 and LSECTin inhibits IFN-γ secretion in vitro and in melanoma cells." (PMID 32861198, 2020). "Depending on the analysed locus (promoter, gene body) we found region-dependent significant LAG3 methylation differences between monocytes, B cells, CD8+ and CD4+ T cells, regulatory T cells, melanocytes, and melanoma cell lines." (PMID 32861198, 2020). "As an approved first-line treatment for advanced melanoma, research into PD1-blockade is more developed than for LAG3-blockade." (PMID 30653605, 2019).
melanoma (continued). "Inhibiting the checkpoints lymphocyte-activation gene 3 (LAG-3) or T-cell immunoglobulin and mucin-domain containing-3 (TIM-3) in combination with PD-1 axis blockade and irradiation enhanced survival of melanoma cell line xenograft-bearing mice." (PMID 31905723, 2019). "Another LAG-3 targeting mAb relatlimab (BMS-986016) alone and in combination with nivolumab is being tested in melanoma patients previously treated with anti-PD-1/PD-L1 therapy (NCT01968109)." (PMID 31554169, 2019). "While blockade of PD-1 or PD-L1 in combination with IL PV-10 therapy led to anti-tumor immunity in murine melanoma, many CD8+ T cells infiltrating tumors express other co-inhibitory molecules including Tim3, Lag3, CD160, CD244 and BTLA." (PMID 29694419, 2018). "Several murine tumor models, including a B16 melanoma and an MC38 colon adenocarcinoma model demonstrated synergistic anti-tumor immunity by dual blockade of PD-1 and LAG-3." (PMID 29535740, 2018). "In a mouse melanoma model, tumor-specific CD4+ effector T-cells showed traits of chronic exhaustion, with high expression levels of PD-1, TIM-3, 2B4, TIGIT, and LAG-3 inhibitory molecules." (PMID 28970830, 2017). "LAG-3 is a transmembrane protein expressed on T regulatory (T reg) cells that binds MHC II, often expressed on melanoma cells, thereby enhancing T reg activity, negatively regulating the cellular immune response, and protecting melanoma cells from apoptosis." (PMID 29546098, 2015). "Clinically, low surface LAG-3 expression coupled with high ADAM10 expression on conventional CD4+ T cells correlates with improved survival and responsiveness to PD-1 blockade in patients with HNSCC and melanoma." (PMID 41486149, 2026). "Interestingly, blocking both PD-1 and LAG-3 resulted in a high enrichment of new clones in the TME with a terminally exhausted and activated phenotype in patients with advanced melanoma and HNSCC." (PMID 40299510, 2025). "LAG-3 is highly expressed in osteosarcoma.One promising combination is the use of relatlimab (anti-LAG-3) alongside nivolumab (anti-PD-1), which has shown encouraging results in melanoma and other solid tumors." (PMID 40170852, 2025). "In melanoma, aged patients often display impaired expansion of tumor‐specific CD8+ T cells following ICI therapy, accompanied by upregulation of exhaustion markers such as PD‐1, LAG‐3, and TIM‐3." (PMID 40926366, 2025). "Clinical evidence from the RELATIVITY-047 trial in melanoma has validated the therapeutic synergy between LAG-3 and PD-1 inhibition, as combining relatlimab (anti-LAG-3) with nivolumab improved outcomes over PD-1 monotherapy, leading to FDA approval in melanoma." (PMID 41013723, 2025). "In melanoma, this exhaustion phenotype is enriched in tumour-reactive CD4+ and CD8+ αβ T cells which demonstrate increased expression of checkpoints including PD-1, CTLA-4, TIGIT, LAG3, TIM3, and CD39." (PMID 41325134, 2025). "Melanoma has been treated with drugs related to immune targets such as CTLA-4, PD-1, and LAG-3." (PMID 40429702, 2025). "In samples from patients with advanced melanoma from RELATIVITY-047 the levels of PD-1+ CD8 T cells in the tumor and blood were similar; however, LAG-3+ and LAG-3+PD-1+ CD8 T cells were substantially higher in tumor (multiplex CODEX analysis) versus blood (flow cytometry)." (PMID 41109920, 2025). "There are a large number of LAG-3-targeted drugs undergoing clinical trials, such as relatlimab, eftilamidol alpha, LAG525, BI754111, TSR-033, and REGN3767, including treatments for melanoma, mesothelioma, breast cancer, lymphoma, myeloma, and leukemia, among other cancers." (PMID 38581716, 2024). "Considering that single-agent LAG3 immunotherapy has not yielded ideal results in melanoma, it is more suitable as an adjunct therapy to PD1 inhibition." (PMID 38951874, 2024).
melanoma (continued). "The results of a clinical trial using Relatlimab (LAG-3 inhibitor) and Nivolumab for neoadjuvant therapy in thirty patients with stage III resectable melanoma or single-metastatic stage IV melanoma showed that 57% of patients had complete remission and 70% had a partial response." (PMID 38835341, 2024). "Additionally, the FDA-approved drug relatlimab, which targets lymphocyte activation gene-3 (LAG-3), is used in combination with nivolumab (a PD-1 inhibitor) for melanoma treatment." (PMID 39301338, 2024). "Treatment with the inhibitor in combination with a LAG-3 blocking antibody produced a cooperative effect, resulting in increased tumor growth suppression, as well as increased levels of granzyme B and IFN-γ in CD8 + T lymphocytes in murine melanoma models." (PMID 39425148, 2024). "In a sensitive in vitro model based on expanded autologous tumor-infiltrating lymphocytes (TILs) and melanoma cell lines obtained from tumor specimens of melanoma patients, LAG-3 and PD-1+LAG-3 inhibition promoted antitumor immune responses in human autologous melanoma/T-cell cocultures." (PMID 38581716, 2024). "LAG-3 operates by attaching to MHC class II molecules on antigen-presenting cells, which suppresses TCR signaling and T cell activation, playing a crucial role in the tumor microenvironment to aid melanoma cells in evading immune detection." (PMID 38474231, 2024). "CD274, PDCD1, CTLA4, and LAG3 were significantly positively correlated with CTHRC1 expression in colon cancer and thyroid cancer; while only CTLA4 was significantly positively correlated with CTHRC1 expression in melanoma." (PMID 39052013, 2024). "Since then, additional agents targeting novel immune checkpoints, such as T-cell immunoglobulin and mucin domain containing 3 (TIM-3), lymphocyte activation gene-3 (LAG-3), and ITIM domain (TIGIT), are being investigated to expand the scope of immunotherapy for melanoma." (PMID 38571962, 2024). "further elucidated the functional and mechanistic roles of LAG-3, demonstrating that both LAG-3 and sLAG-3 transfected cells protect MHC-II-positive melanoma cells from FAS-induced and drug-induced apoptosis, primarily through activation of the MAPK/ERK and PI3K/AKT signaling pathways." (PMID 39743998, 2024). "It is crucial, especially in the context of the introduction of novel immunotherapies (i.e., anti-II ligand lymphocyte activation gene-3 [LAG-3], and tebentafusp) which are being extensively investigated in clinical trials and showing promising results in melanoma patients." (PMID 37444600, 2023). "It is aiming to compare the efficacy of a fixed-dose combination of relatlimab [lymphocyte-activation gene 3 (LAG-3)] antagonist and nivolumab versus nivolumab monotherapy in patients diagnosed with stage III or IV melanoma who have undergone a complete removal of their tumor(s)." (PMID 37627153, 2023). "Early studies have found that in the melanoma context, metastatic lymph nodes were infiltrated not only by T cells (CD4+, CD8+, and Tregs) but also by a substantial percentage of NKT and NK cells that express LAG-3." (PMID 37670328, 2023). "In a clinical trial in patients with previously untreated metastatic or unresectable melanoma (RELATIVITY‐047), inhibition of two immune checkpoints, LAG‐3 and PD‐1, provided a greater benefit with regard to progression‐free survival than inhibition of PD‐1 alone." (PMID 37326144, 2023). "Lastly, we found an inverse relationship between baseline and on-treatment levels of circulating LAG3 transcript-expressing CD8 memory T cells and response to combination PD-1 and CTLA-4 blockade in a clinical trial cohort of melanoma patients profiled by scRNAseq." (PMID 37795090, 2023). "Moreover, co-inhibition of LAG-3 and PD-1 enhanced antitumor activity compared with single-ICI in a mouse model of solid tumors, such as melanoma, colon adenocarcinoma, and fibrosarcoma." (PMID 37179337, 2023).